IL6 (interleukin 6)
Diseases named in the same sentence as IL6 in open-access papers (continued):
Sharing a sentence is not in itself a finding about the gene and the disease.
endothelial dysfunction (continued). "Our data showed employing CRRT as cytokine modulators could be an additional therapeutic strategy to improve septic shock outcomes via the crucial role of IL-6 signaling in endothelial dysfunction." (PMID 37007795, 2023). "Also, VAT, epicardial fat, and vascular tissue secrete proinflammatory cytokines (eg, TNF‐α [tumor necrosis factor‐α], IL‐1 [interleukin‐1], and IL‐6 [interleukin‐6]), which contribute to microvascular endothelial dysfunction and reduced vascular compliance." (PMID 37345755, 2023). "In previous studies, IL-6 induces endothelial dysfunction upregulating adhesion molecules in vitro." (PMID 36677041, 2023). "They suggested that endothelial dysfunction leads to oxidative stress, and pro-inflammatory IL-6 cytokine release as well as disturbance of nitric oxide (NO) signaling may have a major role in monocyte intracellular STAT3 activation." (PMID 37854465, 2023). "The PVAT in lupus mice exhibited increased infiltration of immune cells and expression of pro-inflammatory cytokines (e.g., IL-1β, IL-6, TNFα, IFNγ), along with decreased expression of adiponectin, which likely promotes endothelial dysfunction and vascular wall remodeling." (PMID 37006244, 2023). "In this regard, plasma CRP levels may represent a more appropriate integrated measure of basal IL-6 activity, another potential mechanism that may explain the relationship between inflammation and endothelial dysfunction." (PMID 36407366, 2022). "Previous studies suggested that hyperlipidemia, especially hypercholesterolemia, leads to the augmentation of oxidative and nitrosative stress and enhanced proinflammatory cytokine production (e.g., TNF-α and IL-6), consequently contributing to cardiac and endothelial dysfunction." (PMID 35806390, 2022). "Pentraxin-3 (PTX3) is a plasma protein involving in chronic inflammation and Interleukin-6 (IL-6) as one of the most common molecules contributes to inflammation may promote endothelial dysfunction and the progression of vascular complication." (PMID 35883173, 2022). "Similarly, Sarvottam and Yadav (2014) identified that increased fasting blood glucose levels were significantly and positively correlated with inflammation as assessed by IL-6 concentrations, as well as with an increased endothelial dysfunction." (PMID 34991564, 2022). "While larger scale and pre-clinical studies will be needed, our study could open perspectives to antagonize VCAM or Fractalkine/IL-6 driven activation pathways during organ perfusion in order to limit endothelial dysfunction prior to transplant." (PMID 36032101, 2022). "Eventually, serum tumor necrosis factor-α (TNF-α), interleukin-6 (IL-6), and C-reactive protein (CRP), which respond to inflammatory levels, were eventually elevated, indicating a link between the inflammatory response caused by IR and endothelial dysfunction." (PMID 36589857, 2022). "Moreover, resistin causes endothelial dysfunction by enhancing proinflammatory markers such as MCP-1, TNF-α, IL-6, long pentraxin 3, IL-1β, vascular cell adhesion molecule-1 (VCAM-1), and intercellular adhesion molecule-1 (ICAM-1)." (PMID 35177953, 2022). "Importantly, we specifically investigated TNF-α, Il-6, and sFlt-1 because they are key players in PE pathogenesis and severe endothelial dysfunction." (PMID 35163594, 2022). "IL-6 provides a large contribution to endothelial dysfunction in COVID-19 patients." (PMID 35453563, 2022). "Moreover, the pro-inflammatory cytokines serum tumor necrosis factor-α(TNF-α) and Interleukin-6 (IL-6) have been found increased in the circulation of women with GDM, which are associated with endothelial dysfunction, and also increased in women with PE." (PMID 35252402, 2022). "This is compatible with the increased levels of TNFα and IL-6 measured in our study and may lead to endothelial dysfunction." (PMID 34460845, 2021).
endothelial dysfunction (continued). "These inhibitory effects of DOX on the TLR4/LPS-signaling pathway, including the reduction of the pro-inflammatory cytokines IL-1β and IL-6, could explain the improvement of endothelial dysfunction and diminishing of blood pressure." (PMID 34578849, 2021). "Oscillatory shear stress also promotes generation of reactive oxygen species and production of pro-inflammatory cytokines such as tumor necrosis factor-α (TNF-α) and interleukin-6 (IL-6), thereby further promoting endothelial dysfunction and formation of atherosclerotic plaque." (PMID 33875621, 2021). "Furthermore, we demonstrate that the elimination of one cytokine (IL-6) is sufficient to normalize endothelial dysfunction and to significantly reduce perivascular and vascular leukocyte infiltration rates." (PMID 33669022, 2021). "Plasma levels of interleukin 6 (IL-6) and tumor necrosis factor alpha (TNFα) were analyzed as markers of inflammation, and soluble tumor necrosis factor-like inducer of apoptosis (sTWEAK) as an endothelial dysfunction marker." (PMID 34046003, 2021). "The negative association between omentin, circulating IL-6 and C reactive protein was also shown to be related to endothelial dysfunction." (PMID 34261479, 2021). "Furthermore, interleukin-6 (IL-6) both participates in inflammation and greatly influences the blood vessels; some findings suggest an important role for IL-6 in limiting endothelial dysfunction in response to angiotensin II." (PMID 33628325, 2021). "Interleukin-6 (IL-6) and granulocyte-macrophage colony-stimulating factor (GM-CSF) are the key cytokines involved in mediating systemic inflammation and triggering endothelial dysfunction." (PMID 33489621, 2020). "Another interesting study revealed that IL-6 plays a key role on superoxide anion generation, endothelial dysfunction and vascular remodeling induced by Ang-II, since in carotid arteries from IL-6-knockout mice these effects were remarkedly decreased compared to control mice." (PMID 32848763, 2020). "OA may contribute to the pathogenesis of endothelial dysfunction by releasing cytokines including IL-6, by increasing TNFα production, and by inducing apoptosis, necrosis and oxidative stress." (PMID 33003345, 2020). "We found that GlyNAC supplementation significantly improved plasma concentrations of key biomarkers of inflammation (IL-6, TNFα, hsCRP) and endothelial dysfunction (sICAM1, sVCAM1and E-selectin), but accrued benefits receded after stopping GlyNAC supplementation." (PMID 33007928, 2020). "There is increasing evidence linking IL-6 to endothelial dysfunction and vascular hypertrophy, as well as fibrosis, including SSc; however, the contribution of other IL-6 family members to these pathological processes, especially the activation of ECs, remains relatively understudied." (PMID 32736577, 2020). "The pro-inflammatory cytokine storm, with elevated levels of interleukin-6 (IL-6), IL-2 receptor, and tumor necrosis factor-α, could also participate in endothelial dysfunction and leukocyte recruitment in the microvasculature." (PMID 32546188, 2020). "Hyperuricemia is known to cause, among others, vascular smooth muscle cell proliferation, endothelial dysfunction, and increased IL-6 synthesis, all of which may contribute to the progression of chronic kidney disease." (PMID 32887389, 2020). "Endothelial inflammation via TNF-α, IL-1β, or IL-6 pro-inflammatory cytokines favors leukocyte recruitment, endothelial dysfunction and activation of blood coagulation making interleukin-driven proatherothrombotic processes a potential pharmacological target explored in several clinical trials." (PMID 32019950, 2020). "Interleukin-6 (IL-6) and granulocyte-macrophage colony-stimulating factor (GM-CSF) are the key cytokines involved in mediating systemic inflammation and triggering endothelial dysfunction which precipitates these events." (PMID 33489621, 2020).
endothelial dysfunction (continued). "However, plasma biomarkers linked to inflammation (inflammatory response and endothelial dysfunction) were related to the severity of liver cirrhosis (CTP score), mainly IP-10 and IL-6, which discriminated patients with Child-Pugh B concerning Child-Pugh A." (PMID 32587340, 2020). "Furthermore, IL-6 induced oxidative stress and endothelial dysfunction was attributable to the increase in the expression of vascular angiotensin II type 1 (AT1) receptors." (PMID 32426041, 2020). "Also, adipose tissue function markers such as leptin, adiponectin and interleukin-6 have been reported to change after SGLT2i treatment and to interplay on mediation of endothelial dysfunction." (PMID 31384310, 2019). "SuPAR which is also induced by IL-6, have more direct effect in formation of the atherosclerotic plaques, and therefore, may be a more specific biomarker of endothelial dysfunction in COPD than other circulating mediators." (PMID 30820636, 2019). "Also, the urinary CRP significantly (p < 0.0001) positively correlated with the endothelial dysfunction marker ET-1, inflammatory markers IL-6 and AGP, and oxidative stress marker 8-OHdG." (PMID 31737180, 2019). "The content of the circulating adhesion molecule vCAM-1 was positively correlated with the levels of CRP (r = 0.42), leptin (r = 0.31), TNF-a (r = 0.35) and IL-6 (r = 0.52), indicating the participation of proinflammatory molecules in the formation of endothelial dysfunction (p < 0.05)." (PMID 30871567, 2019). "Another recent study showed that components of the IL-6 trans-signaling system were significantly elevated in more than 200 subjects with MetS and positively correlated with markers of endothelial dysfunction and arterial stiffness, such as E-selectin, ICAM-1 and VCAM-1." (PMID 31550292, 2019). "Elevated IL-6 levels correlate with peripheral vasodilatation as well as endothelial dysfunction." (PMID 30041663, 2018). "Moreover, interaction between TNF-α and IL-6 also exacerbate oxidative stress and reduce phosphorylation of eNOS, contributing to increase endothelial dysfunction in T2DM patients." (PMID 30170601, 2018). "We have observed an inverse relationship between circulating serum magnesium and vWF (a marker of endothelial dysfunction) and IL-6 (a pro-inflammatory cytokine and a marker of inflammation) after taking BMI into account, in line with other populations studies." (PMID 29663176, 2018). "In this small cross–sectional study of adults between 30 and 50 years, endothelial dysfunction was associated with sCD163 but not IL–6 or cIMT." (PMID 29771268, 2018). "Moreover, increased secretion of adipokines such as proinflammatory cytokines like TNFα, IL-6 and leptin can result in endothelial dysfunction, with the possible involvement of the of kidney vasculature." (PMID 30016369, 2018). "Interleukins and particularly, IL-6 may play a multi-functional role in SAA-mediated endothelial dysfunction." (PMID 30597899, 2018). "Serum magnesium was inversely associated with many CVD risk factors including prevalent atrial fibrillation, lung function (FEV1) and markers of inflammation (IL-6), endothelial dysfunction (vWF) and cardiac dysfunction [NT-proBNP and cardiac troponin T (cTnT)]." (PMID 29663176, 2018). "IL-6 induces vasoconstriction and endothelial dysfunction, increases ROS production and tubular atrophy, and could thus contribute to renal injury during intravascular hemolysis." (PMID 29545789, 2018). "Despite its importance, a direct role and underlying mechanism of IL-6 in endothelial dysfunction in the coronary microcirculation of T2D have not been fully elucidated." (PMID 29095915, 2017). "In reconstitution studies, incubation of vessels from IL-6-deficient mice with recombinant IL-6 recapitulates the impaired vascular phenotypes produced by angiotensin II, providing strong and convincing evidence that IL-6 is a critical mediator of angiotensin II-induced endothelial dysfunction." (PMID 29186034, 2017).
endothelial dysfunction (continued). "Other potential serum biomarkers related to the endothelial dysfunction and inflammation are the nitric oxide, the soluble vascular cell adhesion molecule-1, the high-sensitivity C-reactive protein, the tumour necrosis factor-α, the IL-6 and the P-selectin." (PMID 28933368, 2017). "Additionally, IL-6 release represents a key event in the onset and progression of endothelial dysfunction in diabetic vascular complications." (PMID 28714941, 2017). "As IL-6 has many important effects on blood vessels, including endothelial activation, immune cell recruitment, vascular permeability, vascular hypertrophy, and vascular fibrosis, and endothelial dysfunction the discussion of this review will be limited to the effects of IL-6 on the vasculature." (PMID 29186034, 2017). "The biomarkers were representative of several biologic processes: apoptosis (soluble Fas), inflammation (soluble tumor necrosis factor receptor 1, interleukin 6, interleukin 8) and endothelial dysfunction, (angiopoietin 1, angiopoietin 2, and soluble vascular cell adhesion molecule 1)." (PMID 28814331, 2017). "Il-10, on the other hand, has an anti-inflammatory role and may protect against age-related increases in levels of Il-6, oxidative stress, and endothelial dysfunction." (PMID 27270459, 2016). "It has been suggested that increases in Il-10 might protect against age-related increases in Il-6, oxidative stress and endothelial dysfunction, and confer protection for the immune system against the inflammatory stress response." (PMID 27270459, 2016). "Therefore, various biomarkers of inflammation, immune activation, and endothelial dysfunction, mainly IL-6, TNF and C-reactive proteine (CRP), have been found related with CVD incidence also in HIV patients." (PMID 27148878, 2016). "As heightened inflammation is a key feature of endothelial dysfunction and PE, we selected two genes from the inflammation group, one up-regulated (IL6) and one down-regulated (CCL2) for validation at the protein level to further confirm the real-time RT-PCR data." (PMID 27780539, 2016). "Hyperglycemia causes release of proinflammatory cytokines (IL-6, IL-8, IL-18, and TNF-α), diminished bioavailability of nitric oxide with attendant endothelial dysfunction, and increased production of oxygen-derived free radicals with enhanced oxidative stress." (PMID 26273664, 2015). "Measurements of proinflammatory cytokines and oxidative stress in obese children revealed many markers that might contribute to endothelial dysfunction such as higher levels of leptin, resistin, and IL-6 as well as lower levels of adiponectin." (PMID 26011530, 2015). "The adipokines TNF-α and interleukin 6 (IL-6) may furthermore indirectly influence inflammation processes and endothelial dysfunction." (PMID 26580647, 2015). "At baseline, dp-ucMGP and dp-cMGP correlated significantly with the inflammation marker IL-6 (r 0·321 and r 0·308, respectively; P < 0·05) and with markers of endothelial dysfunction von Willebrand factor (r 0·395 and r 0·393; P < 0·01) and VCAM (r 0·399 and r 0·653; P < 0·001)." (PMID 26495126, 2015). "Chedraui Pet al. demonstrated that postmenopausal women with MS displayed higher IL-6 (inflammation) and lower urokinase-type plasminogen activator levels (endothelial dysfunction) which were mainly related to metabolic abnormalities and led to the occurrence of 2 components of MS at the same time." (PMID 25280459, 2014). "In the present study, we investigated the association among sTWEAK and sCD163 plasma concentrations, the sCD163/sTWEAK ratio and other inflammatory, endothelial dysfunction and thrombotic biomarkers (hsCRP, IL-6, sTNFRII, sVCAM-1, ADMA and D-dimer) with the presence of HIV infection." (PMID 24594990, 2014).
endothelial dysfunction (continued). "The degree of endothelial dysfunction produced by 400 and 1000 ng/kg/min Ang II was reflective of parallel increases in plasma IL-6 levels and vascular macrophage content, suggesting that increases in arterial blood pressure precede the development of endothelial dysfunction." (PMID 25400581, 2014). "Leptin, IL-6, and CRP via deduction of nitrite oxide affect the endothelial activities and this process causes vascular contraction, leucocytic adherence, platelets activation, oxidative stress, and thrombosis that will result in endothelial dysfunction." (PMID 25242867, 2014). "Moreover, the increase in plasma IL-6 correlated directly with the degree of endothelial dysfunction and vascular macrophage content." (PMID 25400581, 2014). "Experimental evidence has also established that several proinflammatory cytokines, including IL-6, contribute to endothelial dysfunction which may lead to increased peripheral vascular resistance and consequently hypertension." (PMID 23691280, 2013). "Our findings indicate that genetic deficiency in IL-10 enhanced expression of IL-6 and accelerated endothelial dysfunction suggesting IL-10 normally protects against age-induced endothelial dysfunction." (PMID 24400151, 2013). "On the other hand, the elevated levels of CRP and the pro-inflammatory cytokines, TNF-α and IL-6, reflect the presence of low-grade inflammation in obese subjects with IR that could contribute to endothelial dysfunction." (PMID 24138787, 2013). "A review of multiple studies by Boos and Lip concluded that IL-6 contributes to endothelial dysfunction which may lead to increased peripheral vascular resistance and consequently hypertension." (PMID 23691280, 2013). "However, concerning serum levels of biomarkers for endothelial dysfunction and inflammation, we found low serum levels of IL-6 and high serum levels of sVCAM-1, TNF-α and hs-CRP in Fabry patients than in healthy volunteers." (PMID 24207059, 2013). "Inflammatory biomarkers (CRP, IL-6, fibrinogen), plasma viscosity, endothelial dysfunction markers (VWF, t-PA), and coagulation factors (VIII and IX, but not VII) were significantly higher in cases of MI/CHD death, but not in cases of incident angina compared with those who were CHD event free." (PMID 19682232, 2009). "Apart from IL-6, rheumatoid factor was also predictive of endothelial dysfunction independent of traditional cardiovascular risk factors in the present cohort." (PMID 15899050, 2005). "In multivariable analysis, IL-6 predicted endothelial dysfunction independent of traditional cardiovascular risk factors." (PMID 15899050, 2005). "Otherwise, a high TG/HDL-C ratio may have adverse effects through endothelial dysfunction, chronic low-grade inflammation, increased oxidative stress, such as interleukin-6, and abnormalities in fibrinolysis and coagulation, contributing to the development and progression of arteriosclerosis." (PMID 41283273, 2025). "Additionally, the elevated inflammatory cytokines, including IL-6, IL-8, and IL-17A, may further exacerbate endothelial dysfunction." (PMID 40557145, 2025). "Interleukin 6 (IL-6) increases as a result of hypertension and has important effects on blood vessels, including endothelial activation, immune cell recruitment, vascular permeability, vascular hypertrophy and fibrosis, and endothelial dysfunction, contributing to increased blood pressure." (PMID 40357058, 2025). "Given that prediabetes is marked by low-grade inflammation and early endothelial dysfunction, IL-6 may serve as a marker for detection through sensitive biomarker monitoring in this group, offering a window of opportunity for early intervention before overt macrovascular damage occurs." (PMID 41150802, 2025).